PATZ1 (POZ/BTB and AT hook containing zinc finger 1)
Diseases named in the same sentence as PATZ1 in open-access papers (continued):
Sharing a sentence is not in itself a finding about the gene and the disease.
tumor (42 papers, 2012 to 2026). "Patz1-KO mice exhibit developmental and neoplastic diseases, and the dysregulation of PATZ1 has indeed been implicated in cancer progression and other pathological conditions in mice and humans." (PMID 39201549, 2024). "High PATZ1 was associated with the tumor grade, with pHGG showing higher levels of PATZ1 compared to pLGG." (PMID 31614588, 2019). "The analysis by qRT-PCR of the E-cadherin encoding gene (Cdh1) confirmed its enhanced expression in tumor xenografts derived from PATZ1-expressing cells compared to controls." (PMID 30744101, 2019). "To further investigate the cause of the enhanced tumor engraftment of FRTL5-Ras-PATZ1 cells, we analyzed the stem-like potential of these cells through their capacity to grow as thyrospheres." (PMID 30744101, 2019). "PATZ1 gene has been associated to different types of cancer sometimes working as a tumor suppressor and sometimes as an oncogene, depending on the cellular context." (PMID 27494852, 2016). "Therefore, if the causal role of PATZ1 in the downregulation of tumor PD-L1 expression is confirmed, future work should investigate the possibility that targeting PATZ1 could enhance the efficacy of anti-PD-1/PD-L1 immunotherapy for NSCLC." (PMID 37046851, 2023). "Herein, we present two rare cases of primary CNS NEpTs harboring EWSR1::PATZ1 fusions, a unique clinical course, and co-existing previously undescribed genetic and methylation alterations in this tumor type." (PMID 40575153, 2025). "The development of LUADs in Patz1-knockout mice is consistent with the envisaged tumor suppressor role of PATZ1 in NSCLC." (PMID 37046851, 2023). "Our analysis, conducted in different NSCLC tumor samples and two NSCLC cell lines, indicated that PATZ1 and PD-L1 expressions are negatively associated and that PATZ1 overexpression downregulates PD-L1 expression." (PMID 37046851, 2023). "U118-MG cells overexpressing PATZ1 were subcutaneously injected into nude mice and dissected on the 20th day after tumor bearing." (PMID 35509848, 2022). "The regulation of human tumors by PATZ1 depends on the cellular environment and sometimes acts as a tumor suppressor and sometimes as an oncogene." (PMID 35509848, 2022). "The xenograft model further verified the effects of PATZ1 on tumor growth and tumor cell proliferation in vitro." (PMID 35509848, 2022). "The effects of PATZ1 on cell apoptosis and tumor proliferation were observed in vivo by tumor xenograft mouse model." (PMID 35509848, 2022). "Being the sole molecular finding constant across all tumors analyzed, we postulate that the PATZ1 fusions are a key driver of tumor initiation." (PMID 34417833, 2021). "This high frequency of copy number alterations, including in cases where no RNA data were available, further supports the suggestion that PATZ1 fusion is likely a defining feature of this molecular tumor type." (PMID 34417833, 2021). "In this study, we identified a distinct DNA methylation-based cluster of 60 tumor samples, within which all tumor samples where RNA sequencing was conducted (n = 27) were found to harbour a PATZ1 fusion." (PMID 34417833, 2021). "Given the dysregulation of CDKN1B in various cancers, the knowledge of the direct regulation of CDKN1B by PATZ1 provides a promising perspective in tackling tumor development and progression." (PMID 33598459, 2021). "The unexpected result that tumor engraftment was enhanced in mice injected with PATZ1-expressing cells compared to controls led us to evaluate the impact of PATZ1 on the stem cell potential of these cells." (PMID 30744101, 2019). "The role of PATZ1 in human cancer regulation is debated, as it works sometimes as a tumor suppressor and sometimes as an oncogene, depending on the cellular context." (PMID 31614588, 2019). "A potential oncogenic function for PATZ1 has been described in colorectal cancer, while it acts as a tumor suppressor in the lung and thyroid." (PMID 31614588, 2019).
tumor (continued). "Evidence suggests a role for PATZ1 in cancer, either as an oncogene, tumor suppressor, or double oncogene/tumor suppressor, depending on the tumor type." (PMID 30744101, 2019). "Surprisingly, FRTL5-Ras-PATZ1 cells showed enhanced tumor initiation when engrafted in nude mice, even if their tumor growth rate was reduced compared to that of FRTL5-Ras control cells." (PMID 30744101, 2019). "In other human malignancies, such as Diffuse Large B Cell Lymphomas (DLBCL), the tumor suppressor function of PATZ1 is proapoptotic, achieved by inhibiting and enhancing transcription of BCL6 and BAX, respectively." (PMID 29186807, 2017). "Here we summarize these studies with a focus on the PATZ1 emerging and controversial role in cancer, where it acts as either a tumor suppressor or an oncogene." (PMID 29186807, 2017). "First among them is cancer, where PATZ1 has been indicated as oncogene, tumor suppressor, or double oncogene/tumor suppressor depending on the tumor type." (PMID 29186807, 2017). "We have previously shown that Patz1-knockout mice develop B-cell neoplasias, suggesting a tumor suppressor role for PATZ1 in human NHLs." (PMID 27494852, 2016). "In particular, the frequency of cells with nuclear expression of PATZ1 was low in most FLs (59%) and DLBCL-GCB (53%), supporting the possible tumor suppressor role for PATZ1 mainly in the FL and DLBCL-GCB sub-types." (PMID 27494852, 2016). "Conversely, PATZ1-expressing cells grow slower and the general tumor growth is likely due to those cells in which expression of PATZ1 was lost, which tend to prevail over those expressing PATZ1." (PMID 25595894, 2015). "We next investigated the capacity of FRO/PATZ1 and their controls to generate tumor xenografts in nude mice." (PMID 25595894, 2015). "Several studies suggest a role for PATZ1 in cancer but its cancer-related function as oncogene or tumor suppressor is still debated." (PMID 25595894, 2015). "However, other rare oncogenic fusions such as MN1, PATZ1, BCOR and CIC do appear to be diagnostic for specific tumor types." (PMID 39409964, 2024). "Furthermore, we demonstrated that overexpression of PATZ1 in NSCLC cells attenuates EMT and inhibits malignant features, such as cell proliferation, migration, and invasion, thus suggesting a tumor suppressor role for PATZ1." (PMID 37046851, 2023). "In support of this hypothesis, we show evidence in vitro and in vivo that PATZ1 acts as a tumor suppressor of NSCLC." (PMID 37046851, 2023). "In both cases, a negative regulator of PD-L1 could be a potential tumor suppressor, as is the case of PATZ1." (PMID 37046851, 2023). "Hence the role of PATZ1 as an oncogene or tumor suppressor has been proposed to depend on the cellular context and the presence of interacting proteins." (PMID 33598459, 2021). "However PATZ1/MAZR has also been described to act as an oncogene or tumor suppressor in experimental tumors and human cancer." (PMID 34195082, 2021). "Indeed, the median tumor growth is significantly lower in FRTL5-Ras-PATZ1 than in FRTL5-Ras-Ctrl mice, likely due to a 50% of mice in which the tumor growth was extremely low or regressed up to complete disappearance." (PMID 30744101, 2019). "To deeper investigate phenotypic differences in RET/PTC1TG mice carrying one, two, or no Patz1-null alleles, we analyzed expression of Ki-67 (a typical marker of cell proliferation) by immunohistochemistry on tumor samples from each genotypic group." (PMID 29584698, 2018). "In particular, PATZ1 positivity was associated with more differentiated tumor areas in a same papillary tumor with solid aspects (data not shown)." (PMID 29584698, 2018). "In addition, several studies indicate a role of PATZ1 in carcinogenesis, sometimes working as a tumour suppressor and sometimes as an oncogene, depending on the cellular context." (PMID 28938636, 2017).
tumor (continued). "As for other proteins included in these subnuclear structures, the compartmentalization of PATZ1 and the cooperation with binding partners, might decide about its tumor suppressor function." (PMID 29186807, 2017). "In the present study, we used Nthy-ori 3-1 cells to test the tumor suppressor function of PATZ1." (PMID 29137300, 2017). "A potential tumor suppressor role of PATZ1 has been demonstrated in previous studies." (PMID 29137300, 2017). "Our previous studies in mice have suggested that PATZ1 may act as a tumor suppressor in lymphomagenesis, particularly in the development of NHLs." (PMID 27494852, 2016). "Moreover, consistent with a possible association between PATZ1 expression and mesenchymal-epithelial transition, in tumor areas showing expression of PATZ1 and follicular-like structures we observed positive staining for E-cadherin." (PMID 25595894, 2015). "Overall, this suggests that PATZ1 may act as a tumor suppressor in NSCLC." (PMID 37046851, 2023). "Therefore, the correlation between high PATZ1 and worse EFS may imply a crucial role for PATZ1 in causing tumor recurrence after treatment." (PMID 31614588, 2019). "However, the presence of PATZ1 inhibits sphere growth in vitro and tumor growth in vivo." (PMID 30744101, 2019). "Therefore, a dual oncogene/tumor suppressor role has been suggested for PATZ1 in GBM." (PMID 30744101, 2019). "Consequently, our results obtained in Nthy-ori 3-1 cells may indicate the involvement of PATZ1 as a tumor suppressor in the early stage of carcinogenesis in thyroid follicular epithelial cells." (PMID 29137300, 2017). "Therefore, since PATZ1 downregulation is predictive of a worst prognosis, we could speculate that PATZ1 is responsible of a positive effect of chemotherapy on tumor exacerbation." (PMID 29186807, 2017). "A double oncogenic/tumor suppressor role might be attributed to PATZ1 in malignant gliomas." (PMID 29186807, 2017). "In all these cases, we do not know whether a new cytoplasmic function of PATZ1 is gained, but certainly there is a loss of its nuclear, and possibly tumor suppressive, function." (PMID 29186807, 2017). "Therefore, we propose PATZ1 as a new prognostic marker of DLBCLs, which may act as a tumor suppressor by enhancing apoptosis through inhibiting and enhancing transcription of BCL6 and BAX, respectively." (PMID 27494852, 2016). "Notably, the tumor areas displaying such features were also enriched in PATZ1 expression, supporting the idea that PATZ1 could have a direct role in a mesenchymal to epithelial transition (MET)-like state." (PMID 25595894, 2015). "This molecular distinctiveness – coupled with the tumor’s ventricular localization and glioneuronal morphology – provides strong support for classifying EWSR1::PATZ1-fused tumors as a unique clinicopathological entity." (PMID 40575153, 2025). "Consistently, overexpression of PATZ1 in LUAD cells inhibits cell proliferation, migration, and invasion, suggesting a tumor suppressor role of this gene in NSCLC, likely by counteracting the epithelial–mesenchymal transition." (PMID 37046851, 2023). "All together, these results indicate that PATZ1 has a key role in suppressing malignant features of NSCLC cells, suggesting a putative tumor suppressor role in this tumor type." (PMID 37046851, 2023). "Our results added data suggesting that different histomolecular tumor subtypes seem to be included within the methylation class “NET, PATZ1 fusion-positive”, including non PATZ1 fusions, and that further cases are needed to better characterize them." (PMID 35115049, 2022). "We, therefore, believe it to be likely that these MN1:PATZ1 and EWSR1:PATZ1 fusions are pathognomonic for this novel tumor type." (PMID 34417833, 2021).
tumor (continued). "In conclusion, we demonstrated that PATZ1 expression in FRTL5-Ras cells enhances stemness potential and, as a likely consequence of that, tumor engraftment in nude mice." (PMID 30744101, 2019). "We also show that PATZ1 protein in GBM co-localizes with stem cell markers, is increased in GBM-derived stem cells compared with tumor differentiated cells, and correlates with the capacity of these cells to grow as spheres." (PMID 28938636, 2017). "PATZ1, a POZ-Zinc finger protein, is emerging as an important regulator of development and cancer, but its cancer-related function as oncogene or tumor-suppressor is still debated." (PMID 25595894, 2015). "Due to the limited number of adjacent normal tissue in our local cohort, it was not possible to statistically compare PATZ1 expression in tumor versus non-tumor tissue." (PMID 37046851, 2023). "At the same time, in mice overexpressing PATZ1, the expression of PUMA was also increased, indicating that PATZ1 can also influence the expression of PUMA in vivo, induce tumor cell apoptosis, and thus inhibit tumor growth." (PMID 35509848, 2022). "Nevertheless, the enhanced in vivo engraftment of FRTL5-Ras-PATZ1 compared to FRTL5-Ras-Ctrl cells is not coupled with an enhanced tumor growth." (PMID 30744101, 2019). "Interestingly, confocal microscopy analysis of human GBM specimens showed that PATZ1 was expressed in the NESTIN+ subpopulation, which has been recently shown to be crucial for tumor recurrence after treatment with the chemotherapeutic agent temozolomide." (PMID 28938636, 2017). "Besides, there have been tumor types with NFATC2 and PATZ1 fusion." (PMID 38427070, 2024). "Kaplan–Meyer curves analyzing tumor engraftment in function of the time from injection, followed by Log-rank (Mantell–Cox test), showed a highly significant difference between FRTL5-Ras-PATZ1-injected mice and their controls (P = 0.0018; HR = 0.1914; 95% CI 0.01456-0.2701)." (PMID 30744101, 2019). "No similarity was seen with the recently described HGNET_MN1 tumor type, which is characterized by MN1:BEND2 and MN1:CXXC5 (but not PATZ1) fusions." (PMID 34417833, 2021). "To validate the in silico results, we analyzed PATZ1 expression in 6 GSCs (3 growing in adhesion and 3 growing as spheres in laminin-coated dishes) isolated from patients affected by GBM in comparison with matched non-stem tumor cells." (PMID 28938636, 2017).
cancer (31 papers, 2013 to 2025). A tumor composed of atypical neoplastic, often pleomorphic cells that invade other tissues. "In this framework, the aim of our study was to evaluate the expression of PATZ1, an emerging cancer-related protein suggested as a diagnostic marker in different cancers, in correlation with the expression of PD-L1, a major target of immunotherapy, in NSCLC." (PMID 37046851, 2023). "Remarkably, we found that 1624 (54%) of PATZ1 target genes are cancer-associated genes, showing that PATZ1 target genes significantly overlap with oncogenic signature gene set (Molecular Signatures Database)." (PMID 33598459, 2021). "POZ/BTB and AT-hook-containing zinc finger protein 1 (PATZ1/MAZR) is a transcription factor associated with various cancers." (PMID 33598459, 2021). "In support of this, a subsequent study identified the chromosomal location of PATZ1 as the human fragile site FRA22B with a likely causative role in the generation of cancer-specific rearrangements." (PMID 29186807, 2017). "This necessity of PATZ1 in ESC survival is like the regulatory role of PATZ1 in several cancer studies." (PMID 38385086, 2024). "PATZ1 expression is strongly related to cancer signatures and cellular proliferation, as recently assessed by PATZ1 ChIP-seq and gene expression microarray analyses." (PMID 37046851, 2023). "Our PATZ1 ChIP-seq data revealed that PATZ1 binds to the genomic loci of many cancer-related genes in HepG2 cells." (PMID 33598459, 2021). "Overall these data strongly support the notion that PATZ1 plays a crucial role in cancer through regulation of cell cycle and proliferation genes." (PMID 33598459, 2021). "Interestingly21 showed that in GBM, EWSR1 was often fused with PATZ1, a cancer related gene, worsening the survival rates." (PMID 33762588, 2021). "Our PATZ1 ChIP-seq and gene expression microarray analyses revealed that PATZ1 is strongly related to cancer signatures and cellular proliferation." (PMID 33598459, 2021). "Together, these results suggest that PATZ1 is involved in the regulation of cancer-related genes, especially cell cycle genes, in HepG2 cells." (PMID 33598459, 2021). "In particular, as for other well-known members of this family, such as Bcl-6, PLZF and HIC-1, PATZ1 has been shown to play crucial roles in both development and cancer." (PMID 30744101, 2019). "Further experiments are ongoing in our laboratory to explore the possibility of a direct role of PATZ1 on the CXCR4 promoter in GBM as well as in other cancer-derived cell lines, where PATZ1 appears involved in counteracting EMT." (PMID 28938636, 2017). "The observations in mice are consistent with recent data obtained in some human cancers, where PATZ1 expression is downregulated in malignant versus normal tissues." (PMID 29186807, 2017). "This would highlight the need for searching the negative regulators of PATZ1 involved in this response and use them as valuable targets for an adjuvant cancer therapy." (PMID 29186807, 2017). "Although previous studies reported a cancer-related role for PATZ1, how PATZ1 is involved in the process of carcinogenesis has not been fully elucidated." (PMID 29137300, 2017). "As for other members of the POK family, PATZ1 plays key roles in development and cancer through its involvement in a variety of cellular processes, including cell proliferation, DNA repair, senescence, apoptosis and differentiation." (PMID 27494852, 2016). "Despite an increasing body of evidences is highlighting PATZ1 as a cancer-related gene, little is known about its function." (PMID 25595894, 2015). "To investigate whether the overexpression of PATZ1 plays a role in NSCLC cancer cell function, we analyzed the proliferative, migratory, and invasive abilities of PATZ1- overexpressing A549 and H1299 cells compared to control cells." (PMID 37046851, 2023).